KRAS (KRas proto-oncogene, GTPase)
Diseases named in the same sentence as KRAS in open-access papers (continued):
Sharing a sentence is not in itself a finding about the gene and the disease.
pancreatic ductal adenocarcinoma (continued). "Obesity driven by chronic consumption of high-fat diet (HFD) is a major risk factor for oncogenic KRAS-mediated pancreatic ductal adenocarcinoma (PDAC)." (PMID 30819189, 2019). "KRAS is one of the most frequently mutated proto-oncogenes in pancreatic ductal adenocarcinoma (PDAC) and aberrantly activated in triple-negative breast cancer (TNBC)." (PMID 30654191, 2019). "KRAS mutations and miRNA dysregulation (e.g. miR-21-5p oncomiR) play key roles in Pancreatic Ductal Adenocarcinoma (PDAC), leading to rapid progression of the disease." (PMID 31523393, 2019). "KRAS mutations are present in over 90% of pancreatic ductal adenocarcinomas (PDAC), and drive their poor outcomes and failure to respond to targeted therapies." (PMID 31296870, 2019). "Recent experiments have begun to decipher the functional consequences of the GNAS p.R201C mutation in pancreatic ductal adenocarcinomas, where it modulates KRAS p.G12V initiated neoplasia." (PMID 31337866, 2019). "The primary and the recurrent tumors share the same G12D KRAS mutation (very common in pancreatic ductal adenocarcinoma), but their different morphology suggests discordant mutations in genes that were not considered in our panel of 11 genes." (PMID 30467323, 2019). "KRAS mutations are frequent in pancreatic ductal adenocarcinoma, leading to bad prognosis and resistance to targeted therapies." (PMID 31296870, 2019). "The genetic landscape of pancreatic ductal adenocarcinoma (PDAC) shows nearly ubiquitous mutations of KRAS, which are required for the initiation and progression of pancreatic ductal adenocarcinoma (PDAC)." (PMID 30819189, 2019). "Oncogenic KRAS mutation plays a key role in pancreatic ductal adenocarcinoma (PDAC) tumorigenesis with nearly 95% of PDAC harboring mutation-activated KRAS, which has been considered an undruggable target." (PMID 31467540, 2019). "Pancreatic ductal adenocarcinomas (PDACs) are highly lethal and display exceptionally high frequency of KRAS mutations (94% mutant)." (PMID 31681559, 2019). "Additional mining of TCGA genomics data revealed that GATAD2B is also commonly amplified in KRAS mutant cancers in other lineages, including pancreatic ductal adenocarcinoma, where KRAS is mutationally activated in greater than 90% of cases 4,9,29,30." (PMID 30013058, 2018). "Kirsten rat sarcoma (KRAS) mutation has been found to be an initiating genetic event for the majority of pancreatic ductal adenocarcinomas, with 95% of pancreatic intraepithelial neoplasms harboring KRAS mutations on chromosome 12." (PMID 29382159, 2018). "According to The Cancer Genome Atlas (TCGA) network analyses of typical pancreatic ductal carcinomas, KRAS mutation is the most frequent genomic event (140/150, 93%) while MSI is not observed." (PMID 30043132, 2018). "With greater than 90% of pancreatic ductal adenocarcinoma’s harboring a KRAS mutation, targeting the RAS signaling pathway is an obvious but difficult approach." (PMID 29382159, 2018). "In contrast, KRAS mutation alone cannot distinguish MCP from typical pancreatic ductal adenocarcinomas." (PMID 30043132, 2018). "Activating mutations in the proto-oncogene KRAS are a hallmark of pancreatic ductal adenocarcinoma (PDAC), an aggressive malignancy with few effective therapeutic options." (PMID 29061961, 2017). "Florian Markowetz and colleagues study transcriptional mechanisms influenced by mutated KRAS, which is common in pancreatic ductal adenocarcinomas, and possible implications for disease characteristics and prognosis." (PMID 28141826, 2017).
pancreatic ductal adenocarcinoma (continued). "The oncogene KRAS point mutation was reported by many literatures to be the major molecular event in pancreatic ductal adenocarcinoma (PDAC) and cholangiocarcinoma, as well as pancreatic cystic lesions." (PMID 28042957, 2017). "We also assessed the KRAS/CDK1 SL in cell models of pancreatic ductal adenocarcinoma (PDAC), a disease where where somatic KRAS mutations are prevalent in approximately 90% of cases." (PMID 26881434, 2016). "Both nutrients are essential for growth of pancreatic ductal adenocarcinoma cells with KRAS mutation." (PMID 27924922, 2016). "Oncogenic mutations of the KRAS gene are present in >90% of pancreatic ductal carcinoma, which is an aggressive and deadly cancer." (PMID 25963558, 2015). "Robust ERK1/2 activity, which frequently results from KRAS mutation, invariably occurs in pancreatic ductal adenocarcinoma (PDAC)." (PMID 24568222, 2014). "It is well known that mutations in KRAS oncogene accumulate early in the disease progression and occur in almost all of pancreatic ductal adenocarcinoma (PDAC)." (PMID 24171174, 2013). "This study aimed to detect RBM5 and KRAS expression in pancreatic ductal adenocarcinoma and their association with clinicopathological features." (PMID 23425895, 2013). "In the present study, we investigated the expression of RBM5 and KRAS at mRNA and protein levels and their associations with clinicopathological features in pancreatic ductal adenocarcinoma." (PMID 23425895, 2013). "Hedgehog signaling pathway is normally involved in patterning processes in the developing embryo, but this pathway is frequent deregulation and correlated with the mutation of the KRAS in pancreatic ductal adenocarcinoma (PDAC)." (PMID 24171174, 2013). "KRAS alterations are a hallmark of pancreatic ductal adenocarcinoma (PDAC) found in >90% of tumors." (PMID 41598808, 2026). "Oncogenic KRAS mutations drive metabolic reprogramming in pancreatic ductal adenocarcinoma (PDAC)." (PMID 41545339, 2026). "KRAS mutations occur in over 90% of pancreatic ductal adenocarcinomas (PDACs), most commonly at codon 12, but the clinical implications of codon-specific subtypes in advanced disease remain unclear." (PMID 41303394, 2025). "Understanding the mechanisms underlying Kirsten rat sarcoma (KRAS) mutation‐driven development and progression of pancreatic ductal adenocarcinoma (PDAC) may facilitate the discovery of novel strategies for KRAS‐mutant PDAC (KRASmut‐PDAC) treatment." (PMID 40569151, 2025). "KRAS mutations occur in over 90% of pancreatic ductal adenocarcinoma (PDA) cases." (PMID 39941877, 2025). "KRAS mutations are find in over 90% of pancreatic ductal adenocarcinoma (PDAC) cases, making PDAC exhibit intrinsic resistance to chemotherapy and reshape the immunosuppressive tumor microenvironment (TME), disappointing the clinically preferred chemotherapy-immunotherapy combination." (PMID 40625227, 2025). "Furthermore, KRAS mutation is a marker for pancreatic ductal adenocarcinoma (PDAC) and is associated with key aspects of its biology, such as inflammation, immune escape and metabolic alterations." (PMID 39165358, 2024). "KRAS gene mutations are the most well-known oncogenic abnormalities but their association with glycan alterations in pancreatic ductal adenocarcinoma (PDAC) is largely unknown." (PMID 38528852, 2024). "It has been reported that activating KRAS mutation are found in more than 90% of cases of pancreatic ductal adenocarcinoma and accumulate at codon 12 and 13, therefore, tumor-derived DNA circulating from primary tumor tissue into the bloodstream are of interest as a surrogate marker." (PMID 38277079, 2024). "Over 90% of patients with pancreatic ductal adenocarcinoma (PDAC) have oncogenic KRAS mutations." (PMID 37964407, 2023). "Activating mutations of the KRAS occurs in >90% of pancreatic ductal adenocarcinoma (PDAC) cases." (PMID 36262061, 2023).
pancreatic ductal adenocarcinoma (continued). "Reasoning that MYC is a key effector of RAS pathway signalling and the GTPase KRAS is almost uniformly mutated in pancreatic ductal adenocarcinoma (PDAC), we investigated whether this cancer type exhibits a functional requirement for NUAK1." (PMID 36975767, 2023). "More than 90% of patients with pancreatic ductal adenocarcinoma (PDAC) have KRAS mutations." (PMID 36810451, 2023). "KRAS mutations lead to an abnormal function of these effector molecules, which results in uncontrolled cell proliferation, resulting in cancers such as lung adenocarcinoma and pancreatic ductal adenocarcinoma." (PMID 36619305, 2022). "This retrospective analysis of patients with metastatic and locally advanced pancreatic ductal adenocarcinoma characterizes prognostic or predictive genomic markers for this patient population, with a focus on KRAS mutational variants and their interaction with concurrent molecular alterations." (PMID 36124727, 2022). "KRAS variant alleles may have differential biological properties which impact prognosis and therapeutic options in pancreatic ductal adenocarcinomas (PDA)." (PMID 36124727, 2022). "Analyzing differences in the mutational status of this THCA cell line compared to the other we noticed that CAL-62 cells carry an activating mutation in the KRAS (G12R, c.34G>C) oncogene, the third most common KRAS mutation in pancreatic ductal adenocarcinoma (PDAC)." (PMID 35272691, 2022). "A study of 2552 pancreatic ductal adenocarcinoma (PDAC) patients found that the most common gene alterations were mutations in KRAS and PTEN (59% and 62%, respectively), with differences in prevalence by site of metastasis (p = 0.042 and p = 0.037, respectively)." (PMID 35664782, 2022). "In order to reflect the present bottleneck of immune checkpoint inhibitors in managing this cancer, we mainly provide information associated with the mechanism by which KRAS mutations establish the immunosuppressive milieus in pancreatic ductal adenocarcinomas." (PMID 34069772, 2021). "One group focused on the association of KRAS mutation to FDG-PET radiomics of pancreatic ductal adenocarcinoma patients, concluding that low-intensity textural features were significantly associated with KRAS gene mutational status (AUC = 0.794–0.82, training)." (PMID 34208595, 2021). "Surprisingly, KRAS gene mutation is found in almost all pancreatic ductal adenocarcinomas." (PMID 34069772, 2021). "Interestingly, gHRR mutations also represent a favorable factor in pancreatic ductal adenocarcinoma, being more often associated to the wild-type KRAS gene." (PMID 33800556, 2021). "Oncogenic KRAS mutations are encountered in more than 90% of pancreatic ductal adenocarcinomas." (PMID 32194992, 2020). "Hence, we developed a rapid, accurate, low-cost method for detecting tumor cell-derived DNA from limited amounts of specimens and samples with a low tumor cellularity, to detect KRAS mutations in pancreatic ductal carcinomas (PDA) using digital PCR (dPCR)." (PMID 32704002, 2020). "As previously discussed regarding the issue of tumor heterogeneity, driver gene mutations are homogeneous within a pancreatic ductal adenocarcinoma, thus even if a second lesion derived from a minor molecular subclone it will still have the same KRAS mutation as the primary tumor sample." (PMID 30467323, 2019). "Samples from 13 patients with a BRAF or KRAS variant present in solid tumor tissue from melanoma (N = 8), colorectal adenocarcinoma (N = 3), or pancreatic ductal adenocarcinoma (N = 2) and a corresponding quantifiable variant present in ccfDNA by ddPCR were analyzed." (PMID 30044795, 2018). "The KRAS mutation is the driving force of pancreatic ductal adenocarcinoma (PDAC)." (PMID 30041673, 2018).
pancreatic ductal adenocarcinoma (continued). "A few of these recurrent neoantigens are from known oncogenic drivers, for example, PIK3CA, MAPK1, ERBB2, ERBB3, and also from the KRAS G12D mutation, which we recently identified as a promising recurrent neoantigen-based immunotherapy target in pancreatic ductal adenocarcinoma." (PMID 28670312, 2017). "KRAS is mutated in >90% of pancreatic ductal adenocarcinomas." (PMID 27929127, 2016). "The majority of pancreatic ductal adenocarcinomas involves mutations in the KRAS oncogene with the most common being G12D; therefore, administration of KRASG12D siRNA has the potential to silence KRAS, leading to apoptosis of the cancer cells and, thereby, slowing and halting tumor growth." (PMID 23844368, 2013). "KRAS mutations have been found in >95% of pancreatic ductal adenocarcinomas, while overexpression of Epidermal Growth Factor receptor (EGFR), which induces Ras signaling, was found in 80–90% human head and neck squamous cell carcinomas and 40% of glioblastomas." (PMID 22438909, 2012). "It is possible that the KRAS mutations identified in extra-hepatic bile duct carcinomas in prior studies may represent cases of peri-biliary pancreatic ductal adenocarcinoma." (PMID 21303542, 2011). "Plasma-derived EV-associated KRAS mutations have also been found to drop after surgical resection of pancreatic ductal adenocarcinoma, suggesting that quantification of vesicular KRAS mutation could be adopted for the assessment of tumor burden and therapy response." (PMID 33670185, 2021). "The remaining case (#5) displayed the same KRAS mutation between the primary and the recurrence, but a different morphology, being the primary a conventional pancreatic ductal adenocarcinoma and the relapse a pancreatic ductal adenocarcinoma with micropapillary features." (PMID 30467323, 2019). "Oncogenic KRAS mutations can progress ADM to pancreatic intraepithelial neoplasia (PanIN) and pancreatic ductal adenocarcinoma (PDAC)." (PMID 41922743, 2026). "KRAS-mutant pancreatic ductal adenocarcinoma (PDAC) remains largely refractory to immune checkpoint blockade." (PMID 41797299, 2026). "Oncogenic KRAS induces metabolic rewiring in pancreatic ductal adenocarcinoma (PDAC) characterized, in part, by dependency on de novo pyrimidine biosynthesis." (PMID 40738904, 2025). "In pancreatic ductal adenocarcinoma (PDAC), ~95% of cases harbor an activating KRAS mutation, primarily at codon 12, 13, or 61, with G12D the most common overall (40%)." (PMID 40951926, 2025). "In pancreatic ductal adenocarcinoma (PDAC), this metabolic shift is driven by oncogenic KRAS mutation that promotes glucose use for glycosylation and synthesis of nucleotides." (PMID 40738904, 2025). "In preclinical models of KRAS-mutant pancreatic ductal adenocarcinoma, co-inhibition of CDK4/6 and MAPK signaling pathway improved treatment efficacy." (PMID 40317086, 2025). "For example, ferroptotic pancreatic ductal adenocarcinoma (PDAC) cells release exosomal KRAS oncoproteins, subsequently inducing macrophage M2 polarization." (PMID 40607253, 2025). "KRAS can also be found in pseudocysts and retention cysts, pancreatic neuroendocrine tumors, pancreatic ductal adenocarcinoma, and metastatic cystic neoplasms." (PMID 40622417, 2025).
pancreatic ductal adenocarcinoma (continued). "For instance, siG12D-LODER, a co-polymer composed of poly lactic-co-glycolic acid (PLGA) encapsulating siRNA targeting KRAS G12D, was investigated in pancreatic ductal adenocarcinoma (PDAC) patients." (PMID 39820726, 2025). "The PI3K and MAPK pathways are two prominent mitogenic pathways driving pancreatic ductal adenocarcinoma (PDAC), in part due to the constitutive activation of KRAS, which is mutated in almost all PDAC." (PMID 40227649, 2025). "This study aims to provide a comprehensive review of the Kirsten rat sarcoma viral oncogene (KRAS)-related treatment for patients with PC, especially pancreatic ductal adenocarcinoma (PDAC)." (PMID 40805153, 2025). "In this study, we examined the synergistic potential of camptothecin and sotorasib in KRAS G12C-mutated MIA PaCa-2 and KRAS G12D-mutated PANC-1 pancreatic ductal adenocarcinoma (PDAC) cells." (PMID 40756996, 2025). "The newly developed 3-amino-1,2,4-triazines, targeting PDK, showed promising therapeutic potential for combatting highly aggressive KRAS-mutant pancreatic ductal adenocarcinoma." (PMID 38672579, 2024). "Perineural invasion (PNI) represents a unique biological feature associated with poor prognosis in pancreatic ductal adenocarcinoma (PDAC), especially in the presence of KRAS mutations." (PMID 39488792, 2024). "Therapeutic targeting of KRAS-mutant pancreatic ductal adenocarcinoma (PDAC) has remained a significant challenge in clinical oncology." (PMID 38409090, 2024). "Advanced pancreatic ductal adenocarcinomas (PDACs) respond poorly to all therapies, including the first-line treatment, chemotherapy, the latest immunotherapies, and KRAS-targeting therapies." (PMID 39468013, 2024). "In pancreatic ductal adenocarcinoma (PDAC), the most prevalent KRAS mutations are found at codon 12, with G12D (45%), G12V (35%), and G12R (17%) as dominant forms, alongside less common G12C and G12F mutations." (PMID 39770538, 2024). "MRTX1133 is a non-covalent KRAS G12D inhibitor that showed significant preclinical antitumor activity in KRAS G12D-bearing tumor cells, especially pancreatic ductal adenocarcinoma." (PMID 38846975, 2024). "In the case of pancreatic ductal adenocarcinomas (PDAC), 90–92% harbor mutations in the oncogene KRAS, triggering canonical MAPK signaling." (PMID 38576709, 2024). "Post-translational modifications of proteins in malignant transformation and tumor maintenance of pancreatic ductal adenocarcinoma (PDAC) in the context of KRAS signaling remain poorly understood." (PMID 38821916, 2024). "Pancreatic ductal adenocarcinoma exhibits a high prevalence of activated KRAS, a key player in signal transduction that was considered undruggable until recently." (PMID 38650175, 2024). "In pancreatic ductal adenocarcinoma patients, early results of RMC-6236 suggested an ORR of 20% with a DCR of 87%, with also a marked reduction in the measurement of mutant KRAS alleles in circulating tumor DNA studies." (PMID 38610868, 2024). "In pancreatic ductal adenocarcinoma (PDAC), nearly 90% of all patients harbor a KRAS mutation and these mutations are implicated in the initiation, maintenance, and progression of pancreatic tumors." (PMID 38727236, 2024).